C4A (complement C4A (Chido/Rodgers blood group))
Diseases named in the same sentence as C4A in open-access papers (continued):
Sharing a sentence is not in itself a finding about the gene and the disease.
vitiligo (5 papers, 2011 to 2024). Generalized well circumscribed patches of leukoderma that are generally distributed over symmetric body locations and is due to autoimmune destruction of melanocytes. "This study provides evidence that the CNV of C4, C4A or C4B may associate with the development of GD and <2 copies of C4A may associate with development of vitiligo in patients with GD." (PMID 21943165, 2011). "Our results revealed that deficiency of C4A may enhance the development of vitiligo in GD patients, implying exist of an alternative pathway for the deficiency of complement." (PMID 21943165, 2011). "Complement C4-B and C4-A are also differentially expressed in vitiligo and enhance phagocytosis and local inflammation." (PMID 38715599, 2024). "What is interesting is that although we explored the relationship of C4 CNV to GD as well as other GD clinical features, only the lower copies of C4A, but not C4B, were associated with higher risk of vitiligo." (PMID 21943165, 2011).
anaphylaxis (4 papers, 2016 to 2025). An acute hypersensitivity reaction that occurs from exposure to an allergen. "Bioactive fragments of complement, such as C3a, C4a and C5a, are released during the course of complement activation and are called anaphylatoxins, which cause anaphylactic shock when produced in large amounts and increase vascular permeability." (PMID 26815288, 2016). "In general, C3a and C4a are considered mediators released during anaphylaxis that stimulate VSMC contraction, increase vascular permeability, cause pulmonary vasodilation and hyperresponsiveness of the airways, among other consequences." (PMID 34248989, 2021). "Activation of the complement cascade further liberates potent anaphylatoxins (C3a, C4a and C5a), that play a crucial role in recruitment and activation of a wide range of inflammatory cells as well as anaphylaxis that subsequently initiate anaphylaxis in some individuals." (PMID 41142425, 2025). "In addition, it is presumed that the cause of anaphylaxis is a complement activation-related pseudoallergy (CARPA), in which the pre-existing IgG or IgM antibody to PEG activates complementarily, generating anaphylatoxins (C3a, C4a, and C5a), and causing mast cell degranulation." (PMID 37298704, 2023).
colitis (4 papers, 2020 to 2023). Inflammation of the colon. "Some of these genes have also been associated with an abnormal response to infection (C4A, ENSBTAG00000006864, and IER3), increased/decreased susceptibility to bacterial infection (C4A and ENSBTAG00000006864), or induced colitis (ABCC4 and IER3)." (PMID 32183688, 2020).
leukemia (4 papers, 2017 to 2025). A malignant (clonal) hematologic disorder, involving hematopoietic stem cells and characterized by the presence of primitive or atypical myeloid or lymphoid cells in the bone marrow and the blood. "Following chemotherapy 2 fragments generated from C4 protein (C4a, C4d) and C3 protein (C3g or C3dg) were not only significantly lower than during overt leukemia but also lower than in the post-chemotherapy PBP." (PMID 36109804, 2022). "In addition, dysregulation of C4A, and GPS2, are also known to be involved in the development of leukemia in humans when they are dysregulated." (PMID 33195511, 2020). "Furthermore, our findings indicate up-regulation of genes related to complement (C4A, C4B, and SERPING1) in BM-MSC exposed to leukemia in vivo." (PMID 29137349, 2017).
liver cirrhosis (4 papers, 2020 to 2024). "Serum C4a/C4b also constitute clinically relevant candidate biomarkers in association with KNG1 and HPX, distinguishing patients with HCC and liver cirrhosis." (PMID 33718121, 2020).
pericarditis (4 papers, 2011 to 2021). An inflammatory process affecting the pericardium. "Low total C4, C4A and C4B gene copy numbers are associated with an increased risk for the development of jSLE and associated pericarditis (low total C4, C4A)." (PMID 33569643, 2021).
autoimmune hepatitis (3 papers, 2010 to 2016). Hepatitis caused by autoantibodies. "Scully LJ and associates also reported that a C4A gene deletion is found in patients with autoimmune hepatitis, especially those presenting at a young age." (PMID 24015209, 2013). "It has been reported that children with autoimmune hepatitis have an isolated partial deficiency of the complement component C4, which is genetically determined and is associated with the possession of the silent gene C4AQO at the C4A locus." (PMID 21274335, 2010).
cataract (3 papers, 2023 to 2024). Partial or complete opacity of the crystalline lens of one or both eyes that decreases visual acuity and eventually results in blindness. "In African Americans with POAG, five complement proteins were significantly elevated in the AH samples compared to those with cataracts: C4A (FC = 2.33, p = 0.027), C4B (FC = 1.69, p = 0.015), complement component C7 (FC = 1.38, p = 0.025), F2 (FC = 1.31, p = 0.023), and C3 (FC = 1.21, p = 0.027)." (PMID 37763167, 2023).
celiac disease (3 papers, 2018 to 2026). An autoimmune genetic disorder with an unknown pattern of inheritance that primarily affects the digestive tract. "The C4A deficiency has been linked with coeliac disease, most likely due to linkage disequilibrium with the surrounding HLA-alleles." (PMID 29928053, 2018). "The specific autoimmune conditions were SLE (18.8%, 6/32 vs. 5.8%, 7/120 in C4A deficient patients and controls, respectively, OR = 3.75, 95%CI = 1.16–12.01, p = 0.031) and coeliac disease (12.5%, 4/32 vs. 0%, 0/120 in C4A deficient patients and controls, p = 0.002)." (PMID 29928053, 2018).
polymyositis (3 papers, 2016 to 2023). A rare idiopathic inflammatory myopathy characterized by symmetric proximal muscle weakness and elevated muscle enzymes. "C4A deficiency is relevant in dermatomyositis, HLA-DRB1*03 is important in IBM and both C4A deficiency and HLA-DRB1*03 contribute interactively to risk of polymyositis." (PMID 36171069, 2023).
pulmonary hypertension (3 papers, 2013 to 2025). Increased pressure within the pulmonary circulation due to lung or heart disorder. "In addition, complement components C3 and C4a have been implicated as biomarkers of idiopathic pulmonary hypertension." (PMID 23844025, 2013).
age-related macular degeneration (2 papers, 2016 to 2021). Age-related loss of vision in the central portion of the retina (macula), secondary to retinal degeneration. "Other recent studies have shown that increased copy numbers of C4A offer protection against age-related macular degeneration (AMD)." (PMID 34142199, 2021).
Cognitive impairment (2 papers, 2022 to 2026). Abnormal cognition is characterized by deficits in thinking, reasoning, or remembering. "Of the top 10 most significant proteins, six (PLOD1, MFN2, NGFR, PPP2R5E, C4A/C4B, and ITGAV) have previously been linked to AD and/or cognitive function, underscoring their potential as biomarkers of cognitive impairment." (PMID 42253369, 2026).
colon cancer (2 papers, 2020 to 2022). "The PPI network showed that CD55 and the key complement system components C3, C4A, and C4B are closely related to colon cancer." (PMID 36741376, 2022).
coronary artery stenosis (2 papers, 2021 to 2024). "The analysis showed that apolipoprotein C-II (APOC2), dedicator of cytokinesis protein 2 (DOCK2), ligand 7 (CXCL7) and vitamin D binding protein (VTDB) were activated, and complement 4A (C4A) were suppressed in diabetic patients and were associated with severe coronary artery stenosis." (PMID 34948066, 2021).
Delusion (2 papers, 2021 to 2022). A delusion is a fixed false belief held despite evidence to the contrary. "Most recently, our lab showed that C4A mRNA expression is positively associated with psychotic symptomology, including the severity of delusions." (PMID 36386965, 2022).
encephalitis (2 papers, 2021 to 2025). An acute inflammatory process affecting the brain parenchyma. "The direct cytotoxicity of complement activation has been demonstrated in patients with GAD-Ab-associated encephalitis, who exhibited increased transcriptional levels of complement protein genes (C3, C4A, C4B) and elevated levels of activated complement proteins in the CSF." (PMID 41041342, 2025).
gout (2 papers, 2023 to 2025). A condition characterized by painful swelling of the joints, which is caused by deposition of urate crystals. "Our finding of decreased C4A (a complement cascade initiator) in TM/TWM groups aligns with reports that febuxostat may modulate complement proteins to reduce gout flares." (PMID 41190022, 2025).
Hepatic steatosis (2 papers, 2016 to 2025). Steatosis is a term used to denote lipid accumulation within hepatocytes. "After correcting for multiple comparisons, two proteins remained significant (q < 0.05): C4A (complement factor 4A), which was decreased in hepatic steatosis, and afamin (AFM), which was increased." (PMID 41354933, 2025). "Among 469 detected EV proteins, 60 differed by hepatic steatosis status (p < 0.05), with two proteins remaining significant after multiple testing correction: complement C4A (C4A) and afamin (AFM)." (PMID 41354933, 2025). "In participants with severe hepatic steatosis (n = 43), subgroup analysis showed increased COL18A1, AFM, PRG4, and INHBE and decreased C4A and APOA1." (PMID 41354933, 2025).
lung squamous cell carcinoma (2 papers, 2022 to 2024). "Five of the ten target drug genes are detected in lung squamous cell carcinoma tissues, whereas the expression of CCNA2, APOM, C4A, PKD2L1, and CYP21A2 was not very significant." (PMID 39175755, 2024).
mental disorder (2 papers, 2012 to 2020). A disease that has its basis in the disruption of mental process. "Deficiencies of complement component C4 isotypes, C4A (MIM+120810) and C4B (MIM *120820), have been associated with various autoimmune, inflammatory or infectious diseases as well as with mental disorders and cancer survival." (PMID 22737222, 2012).
relapsing-remitting MS (2 papers, 2019 to 2024). "A more recent study defined elevated plasma C4a levels and elevated C3 levels in CSF of patients with active relapsing-remitting MS (RRMS) potentially providing furthermore follow-up markers for therapeutic efficacy." (PMID 31780883, 2019).
sarcoidosis (2 papers, 2018 to 2025). Sarcoidosis is a multisystemic disorder of unknown cause characterized by the formation of immune granulomas in involved organs. "In addition, sarcoidosis was more commonly diagnosed in C4A deficient patients (12.50%, 4/32 vs. 2.50%, 3/120 OR = 5.571, 95%CI = 1.1789–26.3, p = 0.036, for C4A deficient patients and controls, respectively)." (PMID 29928053, 2018). "We identified nine biomarkers (IL-1β, IL-6, IL-8, IL-13, VEGF, angiogenin, C4a, RANTES, and MCP-1) that significantly differ in the BAL of patients with HP and sarcoidosis and showed that RANTES and IL-6 are associated with fibrotic outcome." (PMID 40725075, 2025). "Additionally, levels of C4a were substantially higher in EGPA than in sarcoidosis (p = 0.03) patients." (PMID 40725075, 2025). "Based on our results, 9 possible biomarkers were identified (IL-1β, IL-6, IL-8, IL-13, VEGF, angiogenin, C4a, RANTES, and MCP-1) out of 18 tested that significantly differ in the BALF of patients with HP and sarcoidosis." (PMID 40725075, 2025). "Sarcoidosis patients had decreased levels of IL-1β, IL-5, IL-8, IL-12p70, TNF-α, angiogenin, C3a, C4a, RANTES, and MCP-1 and increased levels of IL-2, IL-4, IL-6, IL-13, IFN-γ, and VEGF." (PMID 40725075, 2025).
thyroid (2 papers, 2018 to 2022). "We have additionally identified C2 and C4a, a short-lived fragment of C4, in our data, which indicates a higher probability for involvement of the classical and lectin complement pathways in thyroid disease that are activated through antibody-independent pathways." (PMID 29301248, 2018).
acute appendicitis (1 paper, 2025). "Finally, the colocalization analysis identified five shared pleiotropic genes for MDD and acute appendicitis: C4A, FLOT1, LINC00243, MICB, and PRSS16." (PMID 41438618, 2025). "Additionally, through the colocalization analysis, we identified five shared pleiotropic genes between MDD and acute appendicitis: C4A, FLOT1, LINC00243, MICB, and PRSS16." (PMID 41438618, 2025). "And we found that five genes C4A, FLOT1, LINC00243, MICB, and PRSS16 shared the same tissues between MDD and acute appendicitis." (PMID 41438618, 2025). "Finally, we defined three shared genes: PRSS16, ZNF602P, and ZNF204P by TWAS and nine pleiotropic genes C4A, FLOT1, LINC00243, MICB, and PRSS16 by colocalization analysis between MDD and acute appendicitis." (PMID 41438618, 2025).
allergic asthma (1 paper, 2025). A asthma with a basis in a pathological type I hypersensitivity reaction. "In the BAL of patients with non-allergic asthma, we measured decreased concentrations of IL-4, IL-8, IL-13, IFN-γ, C4a, C5a, and MCP-1 and increased concentrations of IL-6, IL-12p70, TNF-α, and C3a." (PMID 40725075, 2025).
breast invasive carcinoma (1 paper, 2023). "Results from the survival analysis showed that the up-regulated genes AKT3 and VDAC1 and the down-regulated genes ADCYAP1R1, GFAP, and C4A were found to be significantly associated with the overall survival of the patients with breast invasive carcinoma." (PMID 37834358, 2023). "We found that the FTD DEGs, AKT3, UBE2N, VDAC1, ADCYAP1R1, C4A, and GFAP showed significant comorbidity in breast invasive carcinoma patients at a p-value < 0.05." (PMID 37834358, 2023).
focal segmental glomerulosclerosis (1 paper, 2024). A renal disorder characterized by sclerotic lesions in the glomeruli. "Previous studies only revealed that C4a levels were higher in patients with focal segmental glomerulosclerosis, suggesting that complement activation contributes to glomerular injury and sclerosis." (PMID 38898508, 2024).
glioblastoma (1 paper, 2017). The most malignant astrocytic tumor (WHO grade IV). "That is, C1q (fold change 4.2; p < 0.001), C1s (; fold change 4.0; p < 0.001) and C4a (fold change 2.1; p < 0.001) were significantly up-regulated in material from patients with glioblastoma as compared to non-tumor controls." (PMID 28880870, 2017).
head and neck cancer (1 paper, 2024). A primary or metastatic malignant neoplasm affecting the head and neck. "C4A, DDX39B, and MICA/B had associations with risk of head and neck cancers of which one, DDX39B, appeared cancer-subtype-specific and was associated with a lower risk of oropharyngeal cancer [OR: 0.24, 95% CI: 0.13 to 0.43; PP4: 0.94]." (PMID 38684708, 2024).
Mitral stenosis (1 paper, 2014). An abnormal narrowing of the orifice of the mitral valve. "This may be the reason for the lower abundances of C3, C4A, C4B and C4b binding protein α chain observed in Mitral Stenosis patients." (PMID 25379033, 2014).
neovascular age-related macular degeneration (1 paper, 2016). "The aim of this study was to investigate the plasma levels of complement C3a, C4a, and C5a in different types of neovascular age-related macular degeneration (nAMD) and whether the levels were related to patients’ responsiveness to anti-VEGF therapy." (PMID 26884800, 2016).
periodontal disease (1 paper, 2021). "For example, the complement components C4A and C4B highly expressed in periodontal disease were found to modulate T cell immune response by stimulating the activation and migration of T cells." (PMID 33869630, 2021).
polyp (1 paper, 2019). A usually exophytic mass attached to the underlying tissue by a broad base or a thin stalk. "FGB (Fibrinogen beta chain) represents significant down-regulation changes in both processes; transformation of normal into polyp tissue and polyp into cancerous tissue, however, C4A expression decreased significantly solely in polyp rather than normal tissue." (PMID 31749922, 2019).
proliferative diabetic retinopathy (1 paper, 2021). Advanced retinopathy due to diabetes mellitus characterized by the formation of new vessels in the retina. "On the other hand, proteomics analysis of vitreous and AH shows proteins that participate in a complementary system: clusterin, complement C3, and C4-A, which are factors that can serve as biomarkers for proliferative diabetic retinopathy (PDR)." (PMID 34575451, 2021).
pulmonary tuberculosis (1 paper, 2014). A bacterial infection that affects the lungs and is caused by Mycobacterium tuberculosis. "MHC complement genes C2, C4, and factor B (FB), and C3 have been studied in an Indian population showing increased frequencies of complete C4A deficiency, BF*FA and C3*F in patients with pulmonary tuberculosis compared with healthy individuals." (PMID 24638111, 2014).
upper respiratory infections (1 paper, 2014). "In the recent report, C4A deficiency was suggested to predispose children and adolescents to recurrent respiratory infections." (PMID 24638111, 2014).
ZIKV infection (1 paper, 2023). "Interestingly, results show induction of components of the complement system that were common to both DENV and ZIKV in the brain such as CfB and C3, but C2 and C4a—components of the classical and lectin pathways, were only induced by ZIKV infection." (PMID 37022660, 2023).